TRIM29 (tripartite motif containing 29)
Diseases named in the same sentence as TRIM29 in open-access papers (continued):
Sharing a sentence is not in itself a finding about the gene and the disease.
pancreatic cancer (17 papers, 2010 to 2024). "In conclusion, we provided evidence that TRIM29 is upregulated in pancreatic cancer tissues and is associated with PC progression." (PMID 34353343, 2021). "TRIM29 expression in various tumor types has found that increased expression of TRIM29 is associated with more aggressive forms of disease including bladder, colorectal, gastric, lung, and pancreatic cancer." (PMID 27145374, 2016). "GJB3, TMPRRS4, GPRC5A, and TRIM29 were all identified previously, as upregulated in pancreatic cancer tissues." (PMID 37779898, 2023). "The phosphorylated MK2 induces TRIM29 phosphorylation, resulting in a radioresistant response by pancreatic cancer cells." (PMID 34988104, 2021). "TRIM29 can also directly bind to Yes-associated protein 1 (YAP1) to reduce its ubiquitination and degradation, and thus promote the proliferation of pancreatic cancer cells." (PMID 34988104, 2021). "Meanwhile, knocking out TRIM29 gene can inhibit the proliferation, migration, and invasion of pancreatic cancer cells in vitro." (PMID 32640423, 2020). "For example, Wang et al23 found that TRIM29 expression correlates with elevated β‐catenin levels in pancreatic cancer, and β‐catenin function is required for TRIM29's oncogenic effects." (PMID 30079558, 2018). "Immunohistochemical analysis showed that the expression of TRIM29 is increased in pancreatic cancers and correlates with high expression levels of β-catenin." (PMID 25797263, 2015). "TRIM29 has been shown to regulate cancer-stem cell-like profiles in pancreatic carcinomas." (PMID 37779898, 2023). "In addition, TRIM29 controls the transcripts of adenylate kinase 4 (AK4) via posttranscriptional regulation to alter the bioenergetics in pancreatic cancer." (PMID 34988104, 2021). "Therefore, collectively, these findings suggest that TRIM29 may be a novel indicator of a poor prognosis in PC and may function as an oncogene in pancreatic cancer progression." (PMID 34353343, 2021). "In addition, TRIM29 is phosphorylated by MAPKAP kinase 2 (MK2) at Ser550 in an ATM-dependent manner and performs a radioprotective function in pancreatic cancer cells." (PMID 35054873, 2022).
viral infection (15 papers, 2017 to 2025). "Meanwhile, NLRP6 and NLRP9b were upregulated in mouse IECs from Trim29IEC-KO mice after virus infection owing to the loss of degradation by TRIM29." (PMID 39396665, 2025). "On contrast, NLRP6 and NLRP9b were upregulated in IECs of intestines from Trim29IEC-KO mice after virus infection owing to the loss of degradation by TRIM29 in vivo." (PMID 39396665, 2025). "Mechanistically, TRIM29 was shown to interacted with MAVS upon viral infection and to mediate its ubiquitination with at the K11-linked ubiquitin chains at K371, K420, and K500." (PMID 33808506, 2021). "Targeting TRIM29 may represent a promising strategy for modulating innate immune responses and treating viral infections and their associated complications." (PMID 40697819, 2025). "According to current studies and RNA-seq data in this study, TRIM29 plays an important role in the macrophage activation of adipose tissue, especially in viral infection and inflammation." (PMID 35911745, 2022). "Knockout of Trim29 increased survival rates of mice after virus infection, due to increased production of type I IFNs, which restricted viral replication." (PMID 33808506, 2021). "In HSV-1 infection model, Trim29-/- mice were resistant to virus infection, indicated by better survival rate and less viral load in organs, with higher IFN-I level in sera." (PMID 29581886, 2018). "Tripartite motif-containing 29 (TRIM29), an E3 ubiquitin ligase, is expressed in various tissues and has been shown to play a pivotal role in modulating the cGAS-STING pathway, IFN production, and innate immune responses associated with viral infections." (PMID 40697819, 2025). "TCM may modulate immune responses by downregulating the expression of TRIM29 and TRIM18, thereby mitigating the inflammatory damage caused by these viral infections." (PMID 39737190, 2024). "It has been recently recognized that tripartite motif containing 29 (TRIM29) plays a negative regulatory role in type I IFN production in response to polyI:C or dsRNA virus infection in bone marrow–derived DCs and macrophages as well as in response to 5′ppp-RNA in murine alveolar macrophages." (PMID 30344524, 2018). "Furthermore, lung histopathology revealed much-reduced edema, alveolar hemorrhage, alveolar wall thickness, and neutrophil infiltration in Trim29-knockout mice as compared to the lung pathology in WT mice after viral infection." (PMID 29038422, 2017). "However, the overall functions of TRIM29 in other types of innate immune cells and in other types of viral infection are largely unknown." (PMID 29581886, 2018). "Both TRIM29 and TRIM18 play pivotal roles in the progression of various virus infections, including viral enteritis, viral myocarditis, and various organ inflammations." (PMID 39737190, 2024). "Collectively, these results demonstrate that TRIM29 is highly induced and accentuates PERK-mediated ER stress and apoptosis in cardiomyocytes, subsequent to cardiotropic virus infections in both human and mouse models." (PMID 38664417, 2024). "TRIM29 was upregulated in IECs from intestines of Trim29fl/fl mice after EMCV or Rotavirus infection in vivo, whereas NLRP6 and NLRP9b were downregulated in IECs of intestines from Trim29fl/fl mice after virus infection owing to the degradation by TRIM29." (PMID 39396665, 2025). "Viral infection could dysregulate the UFL1 expression, thus promoted STING degradation by TRIM29 to prevent excessive production of IFN." (PMID 35871231, 2023). "TRIM29 was upregulated in primary IECs from mouse intestine organoids of Trim29fl/fl mice after EMCV or Rotavirus infection, whereas NLRP6 and NLRP9b were downregulated in mouse IECs from Trim29fl/fl mice after virus infection owing to the degradation by TRIM29." (PMID 39396665, 2025). "Nevertheless, the mode of action of TRIM29 is completely different from that of PLSCR2, as the latter does not alter the production of IFN-I during viral infection." (PMID 30158934, 2018).
breast carcinoma (14 papers, 2013 to 2025). "In contrast to multiple other cancer types where TRIM29 is known to function as an oncogene, it has been reported to act as a tumor suppressor in breast cancer in two previous studies." (PMID 40420099, 2025). "An inverse relationship between TWIST and TRIM29 has been presented with TWIST transcriptionally repressing TRIM29 leading to increased motility and invasiveness of breast cancer cells." (PMID 40420099, 2025). "TRIM29 is differentially methylated in breast cancer subtypes, and its methylation levels correlate well with the expression levels." (PMID 40420099, 2025). "In breast cancer, TRIM29 also exhibits tumor-suppressive effects, and the inhibition of TRIM29 expression is associated with certain tumor malignant phenotypes." (PMID 33824865, 2021). "It has been reported that knockdown of TRIM29 in breast cancer cells was sufficient to induce EMT with increased level of CDH2 and VIM and decreased level of CDH1 via suppression of TWIST." (PMID 29228692, 2017). "Looking more closely at the breast cancers, we noted that TRIM29 was methylated and suppressed mostly in the ER-positive tumors." (PMID 24651077, 2014). "We looked at TRIM29 methylation and expression in the different subtypes of breast cancers within the TCGA data base." (PMID 24651077, 2014). "Interestingly, the expression levels and biological role of TRIM29 varies among different breast cancer subtypes, hence, remain elusive." (PMID 40420099, 2025). "However, overexpression of TRIM29 decreases proliferation in the Luminal A breast cancer cells and HER2 enriched breast cancer in vitro." (PMID 40420099, 2025). "It is interesting to note that TRIM29 expression is altered in multiple breast cancer subtypes and that may explain its heterogenous functional role among different breast cancer subtypes." (PMID 40420099, 2025). "However, it is reported that TRIM29 acts as tumor suppressor in breast cancer through its ability to inhibit TWIST1 and suppress EMT." (PMID 29552313, 2018). "However, TRIM29 is downregulated in other tumors such as breast cancer and prostate cancer." (PMID 33824865, 2021). "In ER+ breast cancer, TRIM39 and TRIM29 knockdown significantly suppresse ER+ breast cancer cell proliferation." (PMID 36261847, 2022). "TRIM29 overexpression at mRNA and protein level is apparent in TNBC compared to all other breast cancer subtypes in TCGA and CPTAC datasets, and its higher expression correlates to worse recurrence free survival in TNBC patients indicating an important role in TNBC." (PMID 40420099, 2025). "Additionally, data from Clinical Proteomic Tumor Analysis Consortium revealed that most subtypes of TNBC, except for the LAR subtype, exhibited an increased protein expression of TRIM29 compared to Luminal and HER2-enriched breast cancer." (PMID 40420099, 2025). "Besides, transcripts ENST00000524816.7 and ENST00000471245.1 were respectively noncoding regions of gene TRIM29 and CKS1B, which were responsible for breast cancer proliferation, metastasis and invasion." (PMID 34094912, 2021). "Furthermore, TRIM29 plays a role in suppressing TWIST1 and the invasive behavior of breast cancer." (PMID 38444019, 2024). "Here, we identified TRIM29, an important member of TRIM family, as a uniquely enriched protein in recurrent TNBC (post neo-adjuvant chemotherapy) using in silico data analysis comparing TNBC with recurrence to those without recurrence, as well as to all other subtypes of breast cancer." (PMID 40420099, 2025).
lung carcinoma (14 papers, 2012 to 2025). "In the downstream of TRIM29, we confirmed that NF-κB was activated after TRIM29 overexpression in lung cancer cells." (PMID 37692503, 2024). "Among these genes, six were already identified in the lung cancer related network of genes associated with RETC634Y signature (TMEM45B, CLDN1, TRIM29, SMUG1, SATB2, and EFNA3)." (PMID 38132167, 2023). "In lung cancer, TRIM29 has been reported to exert its oncogenic effects through activating autophagy flux." (PMID 35845310, 2022). "Owing to its E3 ubiquitin ligase activity, in many cancers, TRIM29 contributes to the ubiquitination of target proteins and tags them for degradation; for example, TRIM29 promotes the progression of lung cancer by stabilising β-catenin." (PMID 34353343, 2021). "TRIM29 can promote lung cancer proliferation through NF-kB induced up-regulation of cyclin D1 and c-Myc." (PMID 27145374, 2016). "This goes in line with previous reports indicating tumor suppressive activity of TRIM29 in estrogen receptor positive luminal breast cells in contrast to oncogenic function in pancreatic and lung cancers." (PMID 24651077, 2014). "Assessing if continuous stimulation of the lung tissues with Cyanobacteria and/or microcystin inhibits TRIM29 process may have important implications for the understanding of innate immunity and pathogenesis of lung cancer." (PMID 30127774, 2018). "TRIM29 upregulates MMP-9 to promote lung cancer cell invasion by activating ERK and JNK pathways." (PMID 27145374, 2016). "Moreover, high expression of TRIM29 correlated with aggressive parameters and poor prognosis in gastric and lung cancers." (PMID 24651077, 2014). "This evidence shows that TRIM29 is a link between EGFR and SLC7A5 in lung cancer cells." (PMID 37692503, 2024). "Interestingly, the top 5 most highly expressed SAE-enriched transcription factors all have previously been established as having a role in airway biology and/or lung cancer, including FOXJ1, ELF3, TRIM29, SOX2, and FOXA1." (PMID 22375630, 2012).
hepatocellular carcinoma (9 papers, 2020 to 2025). A malignant tumor that arises from hepatocytes. "The function of TRIM29 in hepatocellular carcinoma (HCC) is ambiguous, and it has been reported that the silencing of TRIM29 is associated with cell proliferation, tumor formation, cell migration, and cell invasion." (PMID 34988104, 2021). "TRIM29 has been reported preventing hepatocellular carcinoma (HCC) progression by inhibiting Wnt/β‐catenin signalling pathway." (PMID 33683826, 2021). "For example, in a study of hepatocellular carcinoma (HCC), TRIM29 acts as a tumor suppressor, decreasing HCC cell proliferation and clonicity." (PMID 40362175, 2025). "The known mRNA interactors of miR-122 include PKM2, AKT1, MYC, TGFBR1, and SMAD4 in hepatocellular carcinoma, JNK, AP1, and caspases 3/8 in irritable bowel disease, and AKT, PI3K, PCNA, MTDH, PI3K, TRIM29, Bcl-W, CCNG1, and ALDO2 in CRC." (PMID 36499586, 2022).
lymph node metastasis (9 papers, 2009 to 2025). "In this work, we found that of the DEGs, TRIM29 is more highly expressed in tumors than in adjacent normal tissues and is also associated with lymph node metastasis, advanced stage and poor prognosis of CRC." (PMID 33495406, 2021). "TRIM29, a member of the group of RING-less TRIMs, acts as a tumor promoting factor in CRC as implicated by the fact that increased expression levels of TRIM29 observed in CRC patient specimens positively correlates with lymph node metastasis." (PMID 33066016, 2020). "And high expression of mitotic centromere-associated kinesin (MCAK) and tripartite motif-containing 29 (TRIM29) are predictors for lymph node metastasis." (PMID 19737423, 2009). "Low TRIM29 expression was associated with advanced N/M stages and lymph node metastasis." (PMID 37365152, 2023). "In this study, we show that increased levels of TRIM29 were detected in CRC compared with normal tissues and were associated with poor clinical outcome, advanced stage and lymph node metastasis, particularly those with right-sided colorectal cancer (RSCC)." (PMID 33495406, 2021). "It is important to note that the high expression level of TRIM29 is related to the tumour size, lymph node metastasis, and a shorter overall survival in PC patients." (PMID 34353343, 2021). "The expression of TRIM29 is closely related to the depth of tumor invasion, lymph node metastasis, grade and diameter." (PMID 32640423, 2020). "TRIM29 overexpression was closely correlated with tumour size and lymph node metastasis, but did not correlate significantly with age, sex, or tumour location." (PMID 34353343, 2021).
viral myocarditis (9 papers, 2024 to 2025). Myocarditis that is caused by an infection with a viral agent. "TRIM29 deficiency protected mice from viral myocarditis by promoting cardiac antiviral functions and reducing PERK-mediated inflammation and immunosuppressive monocytic myeloid-derived suppressor cells (mMDSC) in vivo." (PMID 38664417, 2024). "Taken together, these data demonstrate that TRIM29 deficiency reduces PERK-mediated immunosuppressive mMDSC to enhance functions of antiviral CD8 T cells during viral myocarditis in vivo." (PMID 38664417, 2024). "TRIM29 could regulate the innate immunity to promote DNA virus HSV-1 infection and loss of TRIM29 mitigates viral myocarditis by attenuating PERK-driven ER stress immune response." (PMID 40144926, 2025). "In this study, we discovered that TRIM29 was an essential regulator of PERK-mediated signaling pathways for causing pathogenesis of viral myocarditis and that the TRIM29-PERK axis could be targeted to reduce viral myocarditis in a mouse model of CVB3-induced myocarditis in vivo." (PMID 38664417, 2024). "Recent findings have highlighted the role of TRIM29 in promoting cardiac injury through the activation of the PERK-mediated ER stress pathway in viral myocarditis." (PMID 39881220, 2025). "Next, we intraperitoneally infected Trim29fl/fl, WTMyHC-Cre and Trim29MyHC-KO mice with the cardiotropic virus CVB3 and further evaluated the importance of cardiomyocyte-specific TRIM29 expression in controlling the pathogenesis of viral myocarditis in vivo." (PMID 38664417, 2024). "In summary, our research offers unprecedented insights into the role of TRIM29-mediated PERK signaling in the pathogenesis of viral myocarditis, underscoring the therapeutic efficacy of PERK inhibitors for its treatment." (PMID 38664417, 2024). "Our findings further elucidate that the PERK inhibitor, GSK2656157, can mitigate viral myocarditis by interfering with the TRIM29-PERK axis." (PMID 38664417, 2024). "TRIM29 has been reported to contribute to the pathogenesis of viral myocarditis by enhancing ROS-mediated oxidation of TBK1, thereby inhibiting its function." (PMID 39737190, 2024). "In essence, our study pioneers the illumination of TRIM29-driven PERK signaling pathways in viral myocarditis pathogenesis, underscoring the therapeutic potential of targeting the TRIM29-PERK axis to combat the disease." (PMID 38664417, 2024). "To pinpoint which among these sensor-mediated signaling pathways intersects with TRIM29 expression during viral myocarditis, we assessed the expression levels of PERK, IRE1α and ATF6 in cardiomyocytes." (PMID 38664417, 2024). "Our work offers compelling in vivo evidence spotlighting the pivotal role of the TRIM29-driven PERK signaling pathway in the pathogenesis of viral myocarditis." (PMID 38664417, 2024). "Compared to Trim29+/+ mice, Trim29-/- mice had less heart weight increase during viral myocarditis, a marker of cardiac inflammatory edema." (PMID 38664417, 2024). "To discern the potential correlation between TRIM29 expression, ER stress, and the pathogenesis of viral myocarditis, we initiated an evaluation of TRIM29 levels in patients diagnosed with cardiomyopathy and in mice model with viral myocarditis." (PMID 38664417, 2024). "As a key negative regulator, TRIM29 deficiency regulates the PERK-mediated ER stress pathway, thereby enhancing local antiviral capacity and conferring protection against both lethal influenza infection and viral myocarditis." (PMID 40612955, 2025). "It was found that TRIM29 (Tripartite motif 29) can regulate alveolar macrophage activation to mitigate bacteria-induced sepsis and controls viral myocarditis by modulating protein kinase RNA-like endoplasmic reticulum kinase (PERK)-mediated ER stress and ROS responses." (PMID 40356926, 2025).